CDK16 (cyclin dependent kinase 16)
Description:
Protein kinase that plays a role in vesicle-mediated transport processes and exocytosis. Regulates GH1 release by brain neurons. Phosphorylates NSF, and thereby regulates NSF oligomerization. Required for normal spermatogenesis. Regulates neuron differentiation and dendrite development (By similarity). Plays a role in the regulation of insulin secretion in response to changes in blood glucose levels. Can phosphorylate CCNY at 'Ser-336' (in vitro).
Synonyms: PCTAIRE1; PCTK1; PCTAIRE; PCTGAIRE; FLJ16665
Tractability: Small molecule: a drug acting on it is in phase 2 or 3 trials; a structure with a bound ligand is known; a high-quality ligand is known; it has a high-quality binding pocket; it belongs to a druggable protein family. Antibody: UniProt places it where antibodies can reach, with high confidence; its Gene Ontology location is reachable by antibodies, with high confidence; the Human Protein Atlas places it where antibodies can reach. PROTAC: it is named in the literature on targeted protein degradation; ubiquitination databases record sites on it; its protein half-life has been measured; a small molecule that binds it is known.
Target class: Kinase; CMGC protein kinase TAIRE subfamily; Enzyme; CMGC protein kinase CDK family; Protein Kinase; CMGC protein kinase group
Chemical probes: JA397 (high quality)
Gene: Protein-coding gene on chromosome X (47,217,860 to 47,230,000, forward strand). Ensembl gene ENSG00000102225.
Subcellular location: Cytoplasm; Cytoplasmic vesicle, secretory vesicle; Cell membrane; Synapse, synaptosome
Subcellular location (Human Protein Atlas): Cytosol; Microtubules; Plasma membrane
Gene Ontology:
Molecular function: protein binding; protein serine kinase activity; protein serine/threonine kinase activity; cyclin-dependent protein serine/threonine kinase activity; ATP binding; protein kinase activity
Biological process: positive regulation of autophagy; regulation of insulin secretion involved in cellular response to glucose stimulus; exocytosis; growth hormone secretion; neuron projection development; protein phosphorylation; regulation of cell cycle phase transition; spermatogenesis
Cellular component: cyclin-dependent protein kinase holoenzyme complex; cytoplasm; cytoplasmic side of plasma membrane; cytosol; plasma membrane; synaptic vesicle; synapse; transport vesicle
Gene-disease validity (ClinGen):
ClinGen rates the evidence that CDK16 causes each of these diseases.
X-linked complex neurodevelopmental disorder (X-linked): Limited. A complex neurodevelopmental disorder that is transmitted via X-linked inheritance, and is characterized by intellectual disability, autism and epilepsy.
Homologues: Orthologues: chimpanzee CDK16 (100% identical), macaque CDK16 (100% identical), rabbit CDK16 (99% identical), pig CDK16 (99% identical), guinea pig CDK16 (98% identical), mouse Cdk16 (98% identical), tropical clawed frog cdk16 (79% identical), zebrafish cdk16 (79% identical), Caenorhabditis elegans pct-1 (55% identical). Paralogues in human: CDK17 (72% identical), CDK18 (61% identical), CDK14 (43% identical), CDK15 (39% identical), CDK12 (36% identical), CDK11B (35% identical), CDK11A (34% identical), CDK13 (34% identical), CDK5 (34% identical), CDK2 (32% identical), CDK3 (32% identical), CDK1 (31% identical), and 14 more.
Diseases named in the same sentence as CDK16 in open-access papers:
CDK16 is named in the same sentence as 46 diseases in open-access papers, as found by Europe PMC text mining. Sharing a sentence is not in itself a finding about the gene and the disease. The quoted sentences say what the papers report.
melanoma (10 papers, 2014 to 2025). A malignant, usually aggressive tumor composed of atypical, neoplastic melanocytes. "We confirmed these findings and showed through analysis of the TCGA melanoma dataset that high expression of CDK16 was associated with a shorter overall survival." (PMID 29112787, 2018). "Combined silencing of NEK9 and CDK16 was associated with enhanced inhibition of melanoma cell proliferation." (PMID 29112787, 2018). "Although the role of CDK16 has been explored previously in melanoma progression, little is known about how NEK9 expression impacts long‐term survival." (PMID 29112787, 2018). "In cell lines of cutaneous SCC, prostate cancer, breast cancer, cervical cancer, and melanoma, knockdown of Cdk16 inhibited cancer cell proliferation, and induced apoptosis over time." (PMID 29629337, 2018). "Silencing of CDK16 through shRNA inhibited the growth of BRAF‐mutant melanoma cell lines in vitro and in vivo." (PMID 29112787, 2018). "CDK16 has also been suggested as a therapeutic target in BRAF‐mutant melanoma with increased expression of the protein reported in melanoma metastases compared to benign nevi." (PMID 29112787, 2018). "Both NEK9 and CDK16 were highly expressed in specimens of advanced melanoma, with high expression of both proteins correlating with a worse overall survival." (PMID 29112787, 2018). "Silencing of CDK16 in both BRAF‐ and NRAS‐mutant melanoma cell lines led to cell cycle arrest associated with expression of p27 and reduced phosphorylation of the RB protein at S780." (PMID 29112787, 2018). "We observed these functions for Cdk16 in various cancer cells (cutaneous SCCs; basal cell carcinomas; prostate, breast, and cervical cancers; and melanomas)." (PMID 29629337, 2018). "Dabrafenib inhibits multiple targets in melanoma cells including CDK16." (PMID 29112787, 2018). "We next explored the link between CDK16 expression and survival in the TCGA melanoma cohort." (PMID 29112787, 2018). "Combined silencing of both CDK16 and NEK9 also led to a significant (P < 0.05) reduction in the growth of both 1205Lu and WM1366 melanoma cell lines." (PMID 29112787, 2018). "NEK9 and CDK16 were chosen for further study based upon their potent inhibition by dabrafenib in in vitro kinase assays, and by preliminary siRNA experiments in which their silencing inhibited the growth of NRAS‐mutant melanoma cells." (PMID 29112787, 2018). "Therapy of Cdk16 siRNA was performed using colorectal cancer HCT116 cells and melanoma A2058 cells." (PMID 29629337, 2018). "miR-33a is a well-known tumor suppressor downregulated in melanoma that targets snail family zinc finger 2 (SNAI2) and hypoxia inducible factor 1 (HIF-1) transcription factors positively regulating EMT and glycolysis, respectively, and tumor-promoting cyclin dependent kinase 16 (CDK16)." (PMID 34638331, 2021). "For example, BRAF inhibitors were used in melanoma therapy, and MS-based chemical proteomics were used to identify never-in-mitosis-gene-A related kinase 9 (NEK9) and CDK16 as unique targets of dabrafenib." (PMID 36338621, 2022).
breast carcinoma (9 papers, 2015 to 2026). "The expression of CDK16 is positively correlated with the risk of metastasis and relapse in breast cancer patients, suggesting that CDK16 may contribute to TNBC metastasis." (PMID 35449080, 2022). "Existing literature has shown that CDK16 modulates tyrosine phosphorylation of PRC1 at the T481 site in breast cancer cells." (PMID 40665337, 2025). "In breast cancer cells, phosphorylation of PRC1 by the CDK16/CCNY complex has been linked to accelerated cell cycle progression and tumor growth." (PMID 40665337, 2025). "Based on Oncomine database, several studies reported that CDK16 is one of the most upregulated genes in breast cancer, compared to normal counterpart." (PMID 39800748, 2025). "Our analysis showed that CDK16 was expressed in all breast cancer subtypes and the highest expression was found in basal-like breast cancer samples." (PMID 35449080, 2022). "In this study, we investigated the clinical relevance of CDK16 in the prognosis of breast cancer patients, and revealed that CDK16 is highly expressed in breast cancers, especially TNBC, and its elevated expression is correlated with poor prognosis." (PMID 35449080, 2022). "Our study provides new insights into the roles of atypical CDKs in cancer, highlights the significance of CDK16 in breast cancer, especially TNBC, and offers a promising target for TNBC therapy." (PMID 35449080, 2022). "Here, we found that CDK16 also phosphorylates Rb, and both TNBC and HR+ breast cancer cells are sensitive to CDK16 inhibition." (PMID 35449080, 2022). "In parallel, we observed that CDK16 knockdown induced apparent growth defects in HR+ breast cancer cells but had only a slight effect on the proliferation of HER2+ cells." (PMID 35449080, 2022). "We found that CDK16 exhibits a distinct expression pattern in breast cancer and has strong clinical relevance, making it a potential therapeutic target for breast cancer, especially TNBC." (PMID 35449080, 2022). "CDK16 is up-regulated in breast cancer with aberrantly high levels in TNBC, and elevated CDK16 expression is correlated with poor prognosis of breast cancer patients." (PMID 35449080, 2022). "In breast cancers, Cdk16 expression was elevated in in situ carcinomas and invasive cancers relative to the expression in normal mammary epithelium." (PMID 29629337, 2018). "In this study, we demonstrated that CDK16 is a critical oncogenic driver in breast cancer." (PMID 35449080, 2022). "CDK16 is highly expressed in breast cancer, particularly in triple-negative breast cancer (TNBC)." (PMID 35449080, 2022). "The elevated CDK16 expression is correlated with poor outcomes in breast cancer patients." (PMID 35449080, 2022). "We further investigated the CDK16 protein expression in breast cancer." (PMID 35449080, 2022). "Moreover, among all breast cancer subtypes, CDK16 was exclusively elevated in TNBC." (PMID 35449080, 2022). "However, it remains unclear whether CDK16 has a role in breast cancer and whether it can be used as a therapeutic target for breast cancer." (PMID 35449080, 2022). "This study employed phosphoproteomic analysis to investigate ARID1A phosphorylation in breast cancer, identifying predominant phosphosites-S363, S1184, and S696-regulated by kinases such as MAPK14, CDK16, and MAPK9." (PMID 41572083, 2026). "Knockdown of CDK16 significantly inhibits the proliferation of TNBC and HR+ breast cancer cells, but only has a slight effect on HER2+ breast cancer cells." (PMID 35449080, 2022). "It is known that CDK16 plays an important role in the development and progression of various cancer cells, such as breast cancer cell MDA-MB-468, colon cancer cell HCT-116, prostatic cancer cell DU-145, etc., rather than breast cancer cell MCF-7." (PMID 37497111, 2023).
prostate carcinoma (5 papers, 2014 to 2023). A carcinoma that arises from epithelial cells of the prostate gland. "In prostate cancers, a comparison of Cdk16 immunostaining with Gleason grade revealed lower expression levels in well-differentiated tumors than in less- differentiated tumors." (PMID 29629337, 2018).
cervical cancer (4 papers, 2014 to 2023). A primary or metastatic malignant neoplasm involving the cervix. "Multiple studies have demonstrated a role for CDK16 in cancer progression, with prostate, breast, and cervical cancer cell lines showing increased expression relative to normal cells." (PMID 29112787, 2018).
hepatocellular carcinoma (4 papers, 2019 to 2025). A malignant tumor that arises from hepatocytes. "A previous study suggested that KCNQ1OT1 facilitated tumor growth by competitively sponging miR‐504 and up-regulating cyclin‐dependent kinase 16 (CDK16) in hepatocellular carcinoma." (PMID 32377169, 2020).
liver cancer (4 papers, 2020 to 2025). An epithelial or non-epithelial malignant neoplasm that arises from the liver. "For example, KCNQ1OT1, a miR-504 sponge that targets cyclin-dependent kinase 16 in liver cancer and cyclin E2, a miR-370 sponge in glioma act as ceRNA by neutralizing miR-9." (PMID 38875399, 2024). "A second report documented the inactivation of the JAK2/STAT3 pathway in a liver cancer model, in a similar fashion: a curcumin analog, GL63, contributes to a decreased expression of circZNF83, a sponge for miR-324-5p, whose target is cyclin-dependent kinase 16 (CDK16)." (PMID 37376060, 2023).
lung carcinoma (4 papers, 2022 to 2024). "CDK16 knockdown caused senescence‐associated phenotypes in lung cancer cell lines." (PMID 34687270, 2022). "Similarly, CDK16‐KD resulted in senescence‐associated phenotypes as observed in lung cancer cells." (PMID 34687270, 2022). "To further substantiate CDK16’s role in promoting cell proliferation, we successfully downregulated its expression in H1299 lung cancer cells using two specific CDK16 shRNAs." (PMID 38261737, 2024). "The results from these assays revealed a significant reduction in the viability of H1299 lung cancer cells following CDK16 knockdown." (PMID 38261737, 2024). "We next explored the downstream targets involved in lung cancer cell senescence induced by CDK16‐KD." (PMID 34687270, 2022). "Although CDK16 is a proto‐oncogene with multiple cellular functions, it remains an open and critical question to determine its exact role in the progress of lung cancer development." (PMID 34687270, 2022). "In conclusion, the present study found an opposite trend of the expression and APA usage in CDK16 between lung cancer and senescent cells." (PMID 34687270, 2022). "Taken together, a possible deduction can be reached that CDK16 3′UTR shortening allows lung cancer cells to escape senescence fate by avoiding miR‐485‐5p targeting on its alternative 3′UTR." (PMID 34687270, 2022). "To examine the possible roles of CDK16 in lung cancer cells, we KD CDK16 in two LUAD ‐related cell lines, A549 and H1299." (PMID 34687270, 2022). "The present study revealed that CDK16 has a new function of inducing senescence in lung cancer cells." (PMID 34687270, 2022). "This study demonstrated for the first time that both CDK16 inhibition and miR‐485‐5p overexpression can induce senescence in lung cancer cells, indicating their potential anticancer capacities." (PMID 34687270, 2022). "For this purpose, transcriptome‐wide comparison between CDK16‐KD and control lung cancer cells (A549 and H1299) was performed using RNA‐seq." (PMID 34687270, 2022). "We observed that CDK16 expression was high in multiple cancer types, including lung cancer, whereas various replicative senescence models displayed low CDK16 expression." (PMID 34687270, 2022). "The APA‐mediated 3′UTR shortening of CDK16 in lung cancer cells enable escaping from miR‐485‐5p binding and consequent transcript degradation." (PMID 34687270, 2022). "CDK16 is highly expressed in lung cancer (LUAD and LUSC) and lowly expressed in senescent human embryonic lung cells (WI38 and MRC_5)." (PMID 34687270, 2022). "Intriguingly, LUAD patients with high CDK16 expression have a lower survival rate compared with those with low CDK16 expression, which suggests that CDK16 probably plays a role in lung cancer progress." (PMID 34687270, 2022). "Consistent with the fact that MYC serves as a widespread transcription factor that can regulate tumor‐specific gene expression, we also found the decreased expression of its target gene PD‐L1 in both CDK16‐KD lung cancer cells." (PMID 34687270, 2022). "Moreover, the preference of proximal CDK16 pA site in lung cancer (LUAD and LUSC) was further verified using corresponding RNA‐seq tracks achieved in TCGA database." (PMID 34687270, 2022). "Moreover, both CDK16 inhibition and miR‐485‐5p overexpression can induce senescence of lung cancer cells and thus promote tumor‐suppressive effects." (PMID 34687270, 2022). "CDK16 depletion in lung cancer has been reported to promote apoptosis, another tumor‐suppressive mechanism in addition to cellular senescence, so we wondered whether miR‐485‐5p can also induce apoptosis in lung cancer cells." (PMID 34687270, 2022). "The present study demonstrated that APA‐mediated 3′UTR length regulation exists in CDK16, a member of the well‐known CDK family, and plays a role in lung cancer cell senescence." (PMID 34687270, 2022).
lung carcinoma (continued). "The present study discovered that CDK16, whose expression is under the regulation of APA and miR‐485‐5p, is a potential target for prosenescence therapy for lung cancer." (PMID 34687270, 2022). "The present study discovers that non‐small cell lung cancer (NSCLC) and senescent cells have opposite trends in CDK16 expression and alternative polyadenylation (APA) usage." (PMID 34687270, 2022). "CDK16 (also known as PCTAIRE1) is a less studied member of the CDK family, but it is widely expressed in mammalian tissues and highly expressed in a variety of cancer types, including prostate, breast, cervical, and lung cancers." (PMID 34687270, 2022).
renal carcinoma (4 papers, 2019 to 2025). A carcinoma arising from the epithelium of the renal parenchyma or the renal pelvis. "A notable study showed that inhibition of the 5hmC epigenetic modification in CCNY/CDK16 promoters impaired the activity of renal cancer stem cells, suggesting the potential effects of CDK16 on cancer stem cells (CSCs)." (PMID 35449080, 2022). "Through molecular biology experiments, we found that the mRNA and protein expression levels of endogenous CCNY and CDK16 were significantly decreased in fisetin‐treated renal cancer stem cells." (PMID 30411496, 2019). "Therefore, in summary, we found that fisetin inhibits the epigenetic mechanism in renal cancer stem cells, that is, fisetin inhibits TET1 expression and reduces 5hmC modification in specific loci in the promoters of CCNY/CDK16 in renal cancer stem cells." (PMID 30411496, 2019). "Thus, we conclude that fisetin inhibits the epigenetic mechanism in renal cancer stem cells, that is, fisetin inhibits TET1 expression and reduces 5hmC modification in specific loci in the promoters of CCNY/CDK16 in HuRSCs." (PMID 30411496, 2019). "Therefore, we suggest that fisetin inhibition of mitosis in renal cancer stem cells is achieved through inhibition of CCNY and CDK16 expression." (PMID 30411496, 2019).
colon cancer (2 papers, 2021 to 2023). "Whereas expression levels of CCNY, CCNYL1, and CDK16 were broadly comparable across all cell types, the average level of CDK14 was more than an order of magnitude lower in colon cancer cells compared to any other tissue included in this analysis." (PMID 34571979, 2021).
glioma (2 papers, 2020 to 2024). A benign or malignant brain and spinal cord tumor that arises from glial cells (astrocytes, oligodendrocytes, ependymal cells). "KCNQ1OT1, an miR-504 sponge that targets CDK16 (cyclin‐dependent kinase 16) in HCC and CCNE2 (cyclin E2), and a miR-370 sponge, in glioma can also act as an ceRNA via neutralizing miR-9." (PMID 32754285, 2020).
Intellectual disability (2 papers, 2015 to 2022). "Finally, we report damaging variants in CDK16 and TRPC5 in patients with intellectual disability or autism spectrum disorders." (PMID 36323681, 2022). "The human cyclin-dependent kinase 16 (CDK16) gene, which encodes the protein kinase PCTAIRE-1 (also known as CDK16), maps to the X chromosome (Xp11.3) whose defects and copy-number variants have been linked to various diseases, including intellectual disability and related disorders." (PMID 26205494, 2015).
male infertility (2 papers, 2015 to 2024). The inability of the male to effect fertilization of an ovum after a specified period of unprotected intercourse. "Our study thus reveals an important role of CCNYL1 in regulating male mouse fertility by cooperating with CDK16 and provides insights into the mechanisms underlying cases of male infertility with similar phenotypes." (PMID 26305884, 2015). "It has been reported that conditional knockout of Cdk16 in mice leads to male infertility; CDK16 protein interacts with CCNY protein, and CCNY is highly expressed in the testis in comparison with its levels in the brain and heart." (PMID 26305884, 2015).